NLRP3 (NLR family pyrin domain containing 3)
Diseases named in the same sentence as NLRP3 in open-access papers (continued):
Sharing a sentence is not in itself a finding about the gene and the disease.
injury (continued). "Recent studies have found that the geniposidic acid in Oldenlandia diffusa Roxb can covalently bind to NLRP3 and inhibit the activation of NLRP3 inflammyome, thereby reducing α-naphthalene isothiocyanate induced cholestatic liver injury." (PMID 36969233, 2023). "Resveratrol alone has been shown to induce autophagy and evoke anti-inflammatory responses in retinal pigment epithelium cells, as well as inhibit NLRP3 inflammasome expression, caspase-1 activation, and IL-1β secretion in a mouse model of acute lung injury." (PMID 37375772, 2023). "This study illustrated, for the first time, that tiliroside targets the AMPK pathway, ameliorating mitochondrial damage, attenuating NLRP3 inflammasome activation, and improving LPS-induced acute lung injury in mice." (PMID 38005247, 2023). "The NF-κB/NLRP3 signaling pathway is responsible for mediating hypobaric hypoxia-induced brain injury and traumatic brain injury-induced neuroinflammation." (PMID 36104611, 2023). "Since NLRP3 is the most abundant molecule among all types of inflammasomes, especially in the CNS, the dynamic activation pattern and roles of the NLRP3 inflammasome in CNS trauma was demonstrated by in vivo and in vitro experiments." (PMID 35186932, 2022). "The long noncoding RNA MEG3 is able to sponge microRNA-7b to upregulate the expression of NLRP3 to promote the aggravation of acute lung injury." (PMID 35547731, 2022). "This is in accordance with previous studies that underlined the importance of IL-1β and IL-18 in mediating the PA-induced acute lung injury and activation of NLRP3 inflammasome." (PMID 36463179, 2022). "This study further demonstrated that chemical inhibition of equilibrative nucleoside transporter (ENT) and genetic deletion of ENT1 inhibited the NLRP3 inflammasome activation and protected against PA-induced acute lung injury." (PMID 36463179, 2022). "RAPA treatment (an inducer of autophagy) significantly improved realgar-induced liver injury and NLRP3 inflammasome activation, while 3-MA (an inhibitor of autophagy) aggravated the realgar-induced liver injury and NLRP3 inflammasome activation." (PMID 35628508, 2022). "A study showed that SIRT3-defcient mice increased the inflammation response and NLRP3 inflammasome activation in endotoxin-induced acute lung injury." (PMID 35923224, 2022). "Luo and colleges also demonstrated that upregulation of HO-1 by hemin inhibited LPS-induced NLRP3 inflammasome activation, reducing IL-1β and IL-18 production in sepsis-induced acute lung injury." (PMID 35326116, 2022). "Taken together, these results suggest that NLRP3 inflammasome regulation of A1/A2 astrocyte phenotype transformation is an important mechanism of CIH-related brain injury." (PMID 36437451, 2022). "ROS can regulate the activation of NLRP3 inflammasome and promote KCs polarization via NF-κB, while ROS also account for one of the major factors leading to liver injury." (PMID 35832027, 2022). "The present study demonstrates that MSCs-specific Notch signaling regulates macrophage XBP1s/NLRP3 activation for orchestrating inflammatory responses in APAP-induced acute liver injury." (PMID 35842731, 2022). "The regulatory effect of NF-κB on NLRP3 inflammasome activation has been confirmed in other acute lung injuries induced by carrageenan [PMID: 28,461,340]." (PMID 35266443, 2022). "Rapamycin inhibits the activation of NOD-like receptor protein 3 (NLRP3) by regulating the mammalian target of rapamycin (mTOR) to treat obstructive sleep apnea-related renal injury." (PMID 35184679, 2022). "Treatment of CO-releasing molecule-2 (CORM-2) both inhibited NLRP3 inflammasome activation in LPS-induced acute lung injury and ER stress-induced inflammation." (PMID 35326116, 2022). "In prior studies, Dexmedetomidine treatments have been shown to alleviate hyperoxia-induced acute lung injury and liver injury through the inhibition of the activation of NLRP3 inflammasomes." (PMID 36139756, 2022).
injury (continued). "The decreased expressions of NF-κB and NLRP3 induced by mitophagy activation alleviate acetaminophen-induced acute liver injury." (PMID 35165294, 2022). "Another study has also shown the contribution of NLRP3 activation toward mechanical stretch-induced lung inflammation-injury and LPS-induced acute lung injury." (PMID 36463179, 2022). "Consistent with this study, resveratrol reduced ROS production and NLRP3 activation in a SIRT1-dependent traumatic brain injury rat model." (PMID 34676022, 2021). "It was postulated that vimentin is essential for the assembly and NLRP3 inflammasome activation and leads to elevation in active IL-1β that participate in lung injuries in rodent models." (PMID 33995030, 2021). "Among the multiple inflammasome complexes, NLRP3 appears to be one of the most relevant components in CNS trauma." (PMID 33463071, 2021). "Xanthohumol activates the AMPK/GSK3β-Nrf2 axis and dampens the Txnip/NLRP3 inflammasome and NF-κB, which reduces oxidative stress and ameliorates LPS-induced acute lung injury." (PMID 34366838, 2021). "In an LPS-induced acute lung injury mouse model, intraperitoneal administration of oridonin reduced the protein levels of NLRP3, caspase-1, ASC, and IL-1β in lung tissues." (PMID 33535473, 2021). "A recent study demonstrated that Notch1 signaling promoted HSF1 activation, which in turn inhibited NLRP3 function and hepatocellular apoptosis, leading to the alleviation of I/R-induced liver injury." (PMID 34504645, 2021). "Blocking TREM-1 with LR12, a TREM-1 antagonist peptide, has shown a significant protective effect on LPS-induced acute lung injury via inhibiting the activation of the NLRP3 inflammasome." (PMID 32984356, 2020). "It is also possible that other priming pathways besides NF-κB induce NLRP3 signaling and contribute to rI/R-induced acute lung injury." (PMID 32652517, 2020). "The activation of the NOD-like receptor pyrin domain containing-3 (NLRP3) inflammasome is involved in hemorrhagic shock-induced acute lung injury and lung endothelial cells damage through inflammatory response and cell pyroptosis." (PMID 33013823, 2020). "Recent studies have shown that the activation of the NLRP3 inflammasome is a critical mediator responsible for the maturation of IL-1β for the development of acute lung injury." (PMID 32110933, 2020). "Our results, for the first time, highlight the significance of NLRP3 inflammasome-mediated microglial pyroptosis in the development of post-cardiac arrest brain injury." (PMID 32703306, 2020). "This study demonstrates that microglial pyroptosis mediated by NLRP3 inflammasome is critically involved in the pathogenesis of post-cardiac arrest brain injury and provides a new therapeutic strategy." (PMID 32703306, 2020). "Here, we report that myeloid Notch1 signaling regulates the NLRP3-driven inflammatory response in ischemia/reperfusion (IR)-induced liver injury." (PMID 31673056, 2020). "Upregulation of miR-16 by agomir significantly decreased the mRNA and protein levels of NF-κB, NOD-like receptor protein 3 (NLRP3) inflammasome, and inflammatory factors in LPS-induced acute lung injury." (PMID 32775445, 2020). "During cholestatic liver injury, multiple factors, such as BA and endotoxemia, contribute to the activation of NLRP3 which represents a host defense to pathogens and damaging signals." (PMID 32296329, 2020). "Our results demonstrate that microglia reveal an early pro-inflammatory response demonstrated by an upregulation of CXCR2, CXCL1 and NLRP3 gene expression following LPS-sensitized HI brain injury in neonatal rats." (PMID 33123073, 2020). "The serum levels of both NLRP3 and HMGB-1 were independent risk factors for 6-month mortality in severe blunt abdominal trauma patients." (PMID 31411276, 2019). "In lipopolysaccharide-induced acute lung injury, Dex inhibited NLRP3 activation through the up-regulation of miR-381 and miR-381-mediated degeneration of NLRP3." (PMID 31383789, 2019).
injury (continued). "For example, MCC950, a selective NLRP3 inflammasome inhibitor, was reported to alleviate the severity of traumatic brain injury in experimental animal models through the suppression of the NLRP3 inflammasome priming process." (PMID 30233319, 2018). "The NLRP3 inflammasome has been demonstrated to play a pivotal role in the development of traumatic brain injury through several kinds of mechanisms including RIP3-related pathway, activation of cortical microglia and so on." (PMID 30233319, 2018). "As a result, inhibiting the NLRP3 inflammasome in CNS serves as a potential and effective pathway for the attenuation of the development of traumatic brain injury." (PMID 30233319, 2018). "In aging-related brain injury and cerebral hemorrhage, inhibiting NLRP3-mediated pyroptosis could be achieved through modulation of the PI3K/AKT pathway." (PMID 40430076, 2025). "This study demonstrated that the interplay of the necroptosis pathway and the NLRP3 inflammasome complex can accelerate age-related liver injury, and young plasma may suppress both the necroptosis and NLRP3 inflammasome pathways." (PMID 40418410, 2025). "Furthermore, cGAS‐STING has been shown to enhance NLRP3 inflammasome activation in models of acute liver injury, indicating a potential mechanistic link in SCI." (PMID 40522023, 2025). "Consistently, the inhibition of the NLRP3 inflammasome, which activates caspase-1 to promote the maturation and release of IL-18, has also been shown to reduce inflammatory cytokines after traumatic brain injury." (PMID 39858411, 2024). "Hence, antioxidant therapy effectively counters ROS-mediated activation of the NLRP3 inflammasome in murine acute liver injury models." (PMID 37743919, 2023). "Thus, Rab11a in macrophages has a fundamental check-point role in TWIK2 plasmalemmal translocation and regulating NLRP3 inflammasome activation and endotoxemia-induced inflammatory lung injury." (PMID 37158595, 2023). "In acute lung injury, the impact of NLRP3 inflammasome could be reduced by inhibiting the expression of PTGS2." (PMID 37920214, 2023). "Therefore, this study aims to investigate the effect of ST on hepatic oxidative injury, inflammation, apoptosis, and the mTOR/NF-κB/NLRP3 signaling pathway in streptozotocin (STZ)-induced liver injury." (PMID 38131990, 2023). "Similarly, previous studies have demonstrated that apelin, the first ligand of APJ, attenuates NLRP3 inflammasome activation in rodent models of acute lung injury, cardiomyopathy, and subarachnoid hemorrhage." (PMID 37540330, 2023). "Our findings suggest that the NLRP3 inflammasome has an important role in CIH-related brain injury, and inhibition of the NLRP3 inflammasome may be a therapeutic target for alleviating and preventing CIH-related brain injury." (PMID 36437451, 2022). "The roles of thioredoxin-interacting protein (TXNIP) and receptor for advanced glycation end-products (RAGE)-dependent mechanisms of NOD-like receptor family, pyrin domain containing 3 (NLRP3) inflammasome-driven macrophage activation during acute lung injury are underinvestigated." (PMID 36232959, 2022). "In conclusion, our findings elucidate the anti-inflammatory and protective efficacy of 5-HMF in LPS-induced acute lung injury, and also demonstrate the key mechanism of its action against NLRP3 inflammasome-related inflammatory disorders via the inhibition of ER stress." (PMID 34966742, 2021). "In conclusion, alveolar macrophage pyroptosis may be involved in the development of acute lung injury and NLRP3/ASC inflammasomes participate in the process." (PMID 33613295, 2021). "The anti-NLRP3 inflammasome and anti-NF-κB properties of SB may confer its protective effects on LPS-induced acute lung injury in mice." (PMID 33535473, 2021). "Similarly, a study on the serum levels of NLRP3, published in 2019 by Kuanxue Sun and Hongwei Xia, showed elevated expression in severe blunt abdominal trauma patients and was also correlated with 6-month mortality in these patients." (PMID 34362072, 2021).
injury (continued). "Furthermore, ISO has been demonstrated to inhibit the activation of NLRP3 inflammasomes in acute lung injury." (PMID 34305534, 2021). "As the neuroprotective effect of diazoxide has already been established, our results raise the point whether blockade of NLRP3 increase might act as a contributing factor to the neuroprotective properties of diazoxide in acute nerve injury." (PMID 33328988, 2020). "In addition, H2S significantly suppressed NLRP3 inflammasome activation and subsequent IL-1β excretion in PQ-induced acute liver injury." (PMID 32064027, 2020). "This study illuminates that microglial pyroptosis mediated by NLRP3 inflammasome is closely related to the severe neuroinflammation after cardiac arrest and critically involved in the pathogenesis of post-cardiac arrest brain injury." (PMID 32703306, 2020). "Second, we analyzed whether targeting macrophage S1PR2 may influence NLRP3 inflammasome priming and activation in cholestatic liver injury." (PMID 32695095, 2020). "In fact, NLRP3 activation has been demonstrated to contribute to multiple diseases by increasing IL-1β and IL-18 secretion and amplifying the inflammatory response, including acute lung injury and acute liver failure." (PMID 32695257, 2020). "Hence, the regulation of NLRP3 inflammasome in our acute kidney injury model conferred protection from subsequent kidney injury." (PMID 30691208, 2019). "NLRP3 inflammasome is involved in the inflammatory responses during acute lung injury (ALI)." (PMID 30126430, 2018). "Additionally, the NLRP3 inflammasome is activated after brain injury, and inhibition of the NLRP3 inflammasome results in decreased inflammation and improved neurological function in a mouse model of brain injury." (PMID 30596792, 2018). "Furthermore, Isorhamnetin was speculated to have cytoprotective potential by suppressing by NLRP3 and caspase 1, in a model of acetaminophen-induced liver injury." (PMID 40257540, 2025). "In summary, we demonstrated that CPCGI effectively inhibited NLRP3 inflammasome activation‐mediated pyroptosis in microglia, both in vitro and in vivo, thereby improving the neuroinflammatory microenvironment and promoting neurological recovery following traumatic brain injury." (PMID 40059065, 2025). "Furthermore, this phenolic acid inhibited NLRP3 inflammasome activation revealed by caspase-1 and IL-1β proteins downregulation in Sprague–Dawley rats with carbon tetrachloride (CCl4)-induced acute liver injury." (PMID 37743919, 2023). "In addition, the aberrant induction of NLRP3 inflammasome also contributes to the development of other complex diseases, including acute lung injury, atherosclerosis, type 2 diabetes, gout, lupus, rheumatoid arthritis, non-alcoholic steatohepatitis, and neurodegenerative disorders." (PMID 38005247, 2023). "Thus, we speculated that Notch-activated MSCs may influence XBP1s/NLRP3-driven inflammatory response during APAP-induced acute liver injury." (PMID 35842731, 2022). "Therefore, inhibiting the activation of NLRP3 inflammasome could be an effective strategy for the treatment of acute liver injury." (PMID 33536915, 2020). "In the CCl4-induced liver injury mice model, the effect of Sal B and 2-DG on plasma lactate was examined, while the expression of Pan Kla, LDHA, NLRP3, and IL-1β proteins was also detected and quantitatively analyzed by immunohistochemistry." (PMID 38202819, 2024). "Inhibition of FOXO1, NLRP3, HSP90, or STAT3 has been reported to promote functional recovery after brain injury." (PMID 39310540, 2024). "Furthermore, Deferoxamine has shown potential in reducing NLRP3 activation through the ROS/NF-κB pathway, influencing microglial polarization, decreasing neutrophil and macrophage infiltration, and inhibiting the release of inflammatory factors following traumatic brain injury." (PMID 38962561, 2024).
injury (continued). "This is consistent with findings from previous literature showing that the inhibition of XBP1 activity reduced NLRP3 inflammasome assembly and caspase-1 processing in a model of hepatic ischemia-reperfusion, thus reducing IRI-triggered liver injury." (PMID 36801911, 2023). "Notably, it may promote IAV-induced acute lung injury (ALI) through interaction with NLRP3." (PMID 37376638, 2023). "Treatment with 15 mg/kg AT13387reduced alveolar inflammation, fibrosis, and NLRP3 staining; blocked activation of ERK and HSP90; and attenuated the deposition of collagen and the development of chronic lung injury and airway hyperreactivity." (PMID 35326496, 2022). "RAGE, NLRP3 and TXNIP expressions were increased in an animal model of acute lung injury, a phenomenon that was reversed by RAGE inhibition." (PMID 36232959, 2022). "Nod-like receptor family pyrin domain containing 3 (NLRP3) inflammasome is essential in the pathogenesis of acute respiratory distress syndrome (ARDS), a fatal clinical syndrome that deteriorated from acute lung injury (ALI)." (PMID 36618363, 2022). "We found that activation of autophagy reduced TXNIP protein levels in the liver tissues of realgar-induced liver injury mice and weakened the interaction between TXNIP and NLRP3." (PMID 35628508, 2022). "CRAMP administration mediated exacerbated mouse heart injury might be associated with enhancing TLR4 and P2X7R/NLRP3 signaling, since CRAMP administration mediated detrimental effects could be entirely reversed by inhibition of TLR4, P2X7R, and NLRP3 inflammasome." (PMID 35410418, 2022). "Further evidence was provided by in vivo study, which showed that disruption of Gli1 reversed myeloid Foxo1 deficiency-mediated cytoprotection, evidenced by augmented IR-induced liver injury and enhanced NEK7/NLRP3 activity." (PMID 33288903, 2021). "Inhibition of the NLRP3 inflammasome by MCC950 reversed mitochondrial dysfunction, lung injury, and apoptosis in RIR-induced lung injury." (PMID 33954183, 2021). "Substantial evidence has been indicated that NLRP3 and NLRC4 inflammasomes possess well-characterized protective functions in alcoholic-induced liver injury." (PMID 33406504, 2021). "Recent evidence showed that, in an in vitro SH SY5Y model and an in vivo model of cerebral trauma induced by PTZ, the administration of MCC950 significantly provided a protective effect, and reduced epileptic neuronal apoptosis by inhibiting NLRP3 inflammasome activation." (PMID 38892264, 2024). "NLRP3-mediated pyroptosis has been shown in studies to promote the expression of CXCL12 in neutrophils, thereby inducing neutrophil migration and aggravating the severity of acute lung injury." (PMID 33613295, 2021). "Therefore, MCC950 as a pharmacological inhibitor of NLRP3 inflammasome may represent a promising and feasible treatment strategy to combat SSH and prevent the development of kidney injury." (PMID 39576390, 2025). "The chemerin/CMKLR1 axis has been proposed to regulate the activation of the NLRP3 inflammasome in Kupffer cells in a mouse model of nonalcoholic fatty liver disease, and a rat model of limb ischemia/reperfusion-acute lung injury." (PMID 32390873, 2020). "However, whether NAPQI is involved in the activation of NLRP3 inflammasome in acetaminophen-induced liver injury has not yet been elucidated." (PMID 33912556, 2021).